C1QBP (complement C1q binding protein)
Description:
Multifunctional and multicompartmental protein involved in inflammation and infection processes, ribosome biogenesis, protein synthesis in mitochondria, regulation of apoptosis, transcriptional regulation and pre-mRNA splicing. At the cell surface is thought to act as an endothelial receptor for plasma proteins of the complement and kallikrein-kinin cascades. Putative receptor for C1q; specifically binds to the globular 'heads' of C1q thus inhibiting C1; may perform the receptor function through a complex with C1qR/CD93. In complex with cytokeratin-1/KRT1 is a high affinity receptor for kininogen-1/HMWK. Can also bind other plasma proteins, such as coagulation factor XII leading to its autoactivation. May function to bind initially fluid kininogen-1 to the cell membrane. The secreted form may enhance both extrinsic and intrinsic coagulation pathways. It is postulated that the cell surface form requires docking with transmembrane proteins for downstream signaling which might be specific for a cell-type or response. By acting as C1q receptor is involved in chemotaxis of immature dendritic cells and neutrophils and is proposed to signal through CD209/DC-SIGN on immature dendritic cells, through integrin alpha-4/beta-1 during trophoblast invasion of the decidua, and through integrin beta-1 during endothelial cell adhesion and spreading. Signaling involved in inhibition of innate immune response is implicating the PI3K-AKT/PKB pathway. Required for protein synthesis in mitochondria. In mitochondrial translation may be involved in formation of functional 55S mitoribosomes; the function seems to involve its RNA-binding activity (By similarity). Acts as a RNA modification reader, which specifically recognizes and binds mitochondrial RNAs modified by C5-methylcytosine (m5C) in response to stress, and promotes recruitment of the mitochondrial degradosome complex, leading to their degradation. May be involved in the nucleolar ribosome maturation process; the function may involve the exchange of FBL for RRP1 in the association with pre-ribosome particles (By similarity). Involved in regulation of RNA splicing by inhibiting the RNA-binding capacity of SRSF1 and its phosphorylation. Is required for the nuclear translocation of splicing factor U2AF1L4 (By similarity). Involved in regulation of CDKN2A- and HRK-mediated apoptosis. Stabilizes mitochondrial CDKN2A isoform smARF. May be involved in regulation of FOXC1 transcriptional activity and NFY/CCAAT-binding factor complex-mediated transcription. May play a role in antibacterial defense as it can bind to cell surface hyaluronan and inhibit Streptococcus pneumoniae hyaluronate lyase. May be involved in modulation of the immune response; ligation by HCV core protein is resulting in suppression of interleukin-12 production in monocyte-derived dendritic cells. Involved in regulation of antiviral response by inhibiting RIGI- and IFIH1-mediated signaling pathways probably involving its association with MAVS after viral infection. Acts as a regulator of DNA repair via homologous recombination by inhibiting the activity of MRE11: interacts with unphosphorylated MRE11 and RAD50 in absence of DNA damage, preventing formation and activity of the MRN complex. Following DNA damage, dissociates from phosphorylated MRE11, allowing formation of the MRN complex. (Microbial infection) Involved in HIV-1 replication, presumably by contributing to splicing of viral RNA. (Microbial infection) In infection processes acts as an attachment site for microbial proteins, including Listeria monocytogenes internalin B (InlB) and Staphylococcus aureus protein A. (Microbial infection) Involved in replication of Rubella virus.
Synonyms: SF2AP32; GC1QBP; HABP1; SF2P32; gC1Q-R; gC1qR; p32; COXPD33
Tractability: Small molecule: it has a binding pocket of medium quality. Antibody: UniProt places it where antibodies can reach, with high confidence; its Gene Ontology location is reachable by antibodies, with high confidence; the Human Protein Atlas places it where antibodies can reach. PROTAC: ubiquitination databases record sites on it; its protein half-life has been measured.
Gene: Protein-coding gene on chromosome 17 (5,432,777 to 5,448,830, reverse strand). Ensembl gene ENSG00000108561.
Subcellular location: Mitochondrion matrix; Nucleus; Nucleus, nucleolus; Cell membrane; Secreted; Cytoplasm
Subcellular location (Human Protein Atlas): Plasma membrane; Mitochondria; Predicted to be secreted
Pathways (Reactome):
Immune System: FXIIa activates plasma kallikrein-kinin system; Regulation of FXIIa and plasma kallikrein activity
Signal Transduction: RHOA GTPase cycle; RHOC GTPase cycle
Disease: Defective Intrinsic Pathway for Apoptosis Due to p14ARF Loss of Function
Programmed Cell Death: Apoptotic factor-mediated response
Gene Ontology:
Molecular function: C5-methylcytidine-containing RNA reader activity; complement component C1q complex binding; enzyme inhibitor activity; hyaluronic acid binding; kininogen binding; protein binding; transcription corepressor activity; transcription factor binding; adrenergic receptor binding; mitochondrial ribosome binding; mRNA binding; protein kinase C binding
Biological process: cytosolic ribosome assembly; mitochondrial RNA catabolic process; negative regulation of defense response to virus; negative regulation of double-strand break repair via homologous recombination; negative regulation of interleukin-12 production; negative regulation of MDA-5 signaling pathway; negative regulation of mRNA splicing, via spliceosome; negative regulation of RIG-I signaling pathway; negative regulation of transcription by RNA polymerase II; negative regulation of type II interferon production; phosphatidylinositol 3-kinase/protein kinase B signal transduction; positive regulation of apoptotic process; positive regulation of cell adhesion; positive regulation of dendritic cell chemotaxis; positive regulation of neutrophil chemotaxis; positive regulation of phosphatidylinositol 3-kinase/protein kinase B signal transduction; positive regulation of substrate adhesion-dependent cell spreading; positive regulation of trophoblast cell migration; regulation of complement activation; immune response; positive regulation of mitochondrial translation
Cellular component: cell surface; cytoplasm; cytosol; membrane; mitochondrial matrix; mitochondrion; nucleus; plasma membrane; extracellular region; GABA-ergic synapse; glutamatergic synapse; nucleolus; presynaptic active zone
Genetic constraint (gnomAD): Loss-of-function variants: 24 observed, 29.22 expected, observed/expected ratio (o/e) 0.82, 90% interval 0.59 to 1.15. The synonymous counts are far from expectation, so gnomAD's model fits this gene poorly and the ratio says little. Missense variants: 337 observed, 347.63 expected, observed/expected ratio (o/e) 0.97, 90% interval 0.89 to 1.06. Synonymous variants: 182 observed, 144.09 expected, observed/expected ratio (o/e) 1.26, 90% interval 1.12 to 1.43.
Gene-disease validity (ClinGen):
ClinGen rates the evidence that C1QBP causes each of these diseases.
mitochondrial disease (autosomal recessive): Definitive.
Homologues: Orthologues: chimpanzee C1QBP (99% identical), macaque C1QBP (94% identical), rat C1qbp (86% identical), mouse C1qbp (86% identical), pig C1QBP (85% identical), guinea pig C1QBP (83% identical), dog C1QBP (78% identical), tropical clawed frog c1qbp (66% identical), zebrafish c1qbp (62% identical), Drosophila melanogaster P32 (32% identical), Caenorhabditis elegans cri-3 (22% identical).
Diseases named in the same sentence as C1QBP in open-access papers:
C1QBP is named in the same sentence as 118 diseases in open-access papers, as found by Europe PMC text mining. Sharing a sentence is not in itself a finding about the gene and the disease. The quoted sentences say what the papers report.
breast carcinoma (26 papers, 2015 to 2025). "By analyzing TCGA bulk tissue RNA profiles, we found that dual enhancement of VTN and C1QBP was associated with a worse prognosis in basal-like breast cancer patients compared to patients with high or low expression of either gene." (PMID 38773982, 2024). "Using the results from the TCGA database, we found C1QBP mRNA levels in breast cancer tissues were associated with the levels of VCAM-1." (PMID 33708767, 2021). "In this study, we examined the functional role of C1QBP in promoting the cellular proliferative process and identified potential signaling pathways that could mediate C1QBP-associated tumor growth and progression in breast cancer." (PMID 36674861, 2023). "The overexpression of C1QBP was associated with distant metastasis of breast cancer." (PMID 34067437, 2021). "Expression of C1QBP is also associated with proliferation and metastasis in breast cancer cells." (PMID 30991713, 2019). "In order to investigate the in vivo effects of PDBAG1 and C1QBP, we employed an orthotopic breast cancer tumourigenesis nude mice model for validation." (PMID 39748215, 2025). "Previous studies have shown increased expression of C1QBP across different malignancies particularly in breast cancer where it serves as a master regulator of mitochondrial homeostasis and metabolism." (PMID 39748215, 2025). "As our studies revealed two candidate ligand-receptor pairs, Vtn-C1qbp and Hapln1-Vcan, we further analyzed the correlation between the levels of Vtn and Hapln1 and the prognosis of basal-like breast cancer." (PMID 38773982, 2024). "C1QBP plays a carcinogenic role in various tumors such as colon cancer, breast cancer, and lung cancer." (PMID 39726754, 2024). "Scully investigated the role of C1QBP as a promising molecular target in breast cancer progression, focusing on its impact on cancer cell growth, especially in TNBC MDA-MB-231 cells." (PMID 39000458, 2024). "In this present study, silencing of C1QBP in triple negative MDA-MB-231 breast cancer cells was concomitant with reduced cell proliferation and a diminished rate of cell growth." (PMID 36674861, 2023). "Stable knockdown of the C1QBP gene has also been previously shown to inhibit cell proliferation in MDA-MB-231 breast cancer cells." (PMID 36674861, 2023). "MDA-MB-231 breast cancer cells were selected for experimentation since it is known to have a high expression of C1QBP." (PMID 36674861, 2023). "In this study, the role of C1QBP in breast cancer progression, in particular cancer cell growth, was determined in triple negative MDA-MB-231 breast cancer cells." (PMID 36674861, 2023). "On the other hand, as demonstrated in our present study, overexpression of the C1QBP protein elicited the opposite effect by enhancing cell proliferation in the breast cancer cells." (PMID 36674861, 2023). "High expression of C1QBP has been observed to be a potential breast cancer prognostic marker for regional spread to axillary lymph nodes, distant metastasis, tumor recurrence and poor survival." (PMID 36674861, 2023). "This is unexpected and the mechanism by which C1QBP negatively resulted the ATP levels in breast cancer and HCC cells need to be further studied." (PMID 35711850, 2022). "These proteins regulate the process of post-translational modification, indicating that there exists post-translational modification of C1QBP protein in breast cancer." (PMID 33708767, 2021). "Further analysis using PAM50 typing showed that C1QBP expression in TNBC was the highest among all the molecular subtypes of breast cancer." (PMID 33708767, 2021). "Using the results from The Cancer Genome Atlas database (TCGA) database, we found C1QBP mRNA levels to increase in breast cancer tissues concomitantly with the increasing levels of HIF-1α." (PMID 33708767, 2021). "Firstly, the functions of C1QBP in other subtypes of breast cancer are still unclear and deserved to be explored." (PMID 33708767, 2021).
breast carcinoma (continued). "C1QBP levels were associated with the expression of VCAM-1, P65 and HIF-1α in patients with breast cancer patients, especially in TNBC." (PMID 33708767, 2021). "The relative expression of C1QBP in 144 primary breast tissues versus 14 breast carcinomas was analyzed in the Curtis dataset." (PMID 30991713, 2019). "Overall, these data-driven results suggest that expression of C1QBP is significantly upregulated in breast cancer cells and is positively correlated with patient poor survival." (PMID 30991713, 2019). "In the Curtis dataset, all types of breast cancers were found to have significantly higher expression of C1QBP than their normal counterparts." (PMID 30991713, 2019). "To examine the expression of C1QBP in breast cancer and their corresponding normal counterparts, we analyzed datasets in the Oncomine and TCGA database." (PMID 30991713, 2019). "High levels of C1QBP are found in highly migratory breast cancer cells and its downregulation inhibits wound healing and cell migration." (PMID 30221321, 2019). "C1QBP expression was significantly upregulated in breast carcinomas, compared to the normal breast tissue (p = 3.94E−4)." (PMID 30991713, 2019). "Additionally, we analysed the expression and prognostic value of C1QBP using TCGA breast cancer data." (PMID 39748215, 2025). "The down‐regulation of C1QBP suppresses breast cancer progression but enhances the glycolytic activity of cancer cells, suggesting that p32 may serve as a promising diagnostic molecule and therapeutic target for maintaining metabolic balance in cancer biology." (PMID 39748215, 2025). "Therefore, we carried out gene expression profiling to decipher the role of C1QBP in metastatic breast cancer and identify potential cancer signalling transduction pathways." (PMID 36674861, 2023). "Consistent with this line of investigation, we have previously shown that C1QBP is a proliferative marker in breast cancer tissue samples, and depletion of C1QBP protein in other breast cancer sub-types such as progesterone receptor positive T47D cells decreased cell proliferation and growth." (PMID 36674861, 2023). "Taken together, these findings provide a deeper comprehension of the role of C1QBP in triple negative breast cancer, and could possibly pave the way for future advancement of C1QBP-targeted breast cancer therapy." (PMID 36674861, 2023). "Furthermore, preliminary studies have shown that C1QBP targeted therapy, such as using anti-C1QBP antibodies in breast cancer, and C1QBP inhibitor in glioma have a potential therapeutic value." (PMID 36674861, 2023). "In addition, this multifunctional protein has been identified as a potential therapeutic target, as several studies have demonstrated that knockdown of C1QBP inhibit proliferation, migration and metastasis of breast cancer cells." (PMID 36674861, 2023). "Furthermore, C1qbp silencing in MDA-MB-231 breast cancer cells reduces proliferation, migration, and induces doxorubicin-induced apoptosis." (PMID 34711805, 2021). "We have shown that C1QBP is an oncogene which is highly expressed in breast cancer tissues." (PMID 33708767, 2021). "Similarly, among breast cancer patients with metastasis or dead, the expression level of C1QBP in TNBC is still higher than that in other subtypes." (PMID 33708767, 2021). "Several studies have revealed the functions of C1QBP in tumorigenesis are varied: for instance, C1QBP maintains oxidative phosphorylation for tumor cells, enhances cell chemotaxis and metastasis in breast cancer and suppresses the Y box binding protein 1 in renal cell carcinoma." (PMID 32025240, 2020).
breast carcinoma (continued). "The same investigators observed that C1QBP modulate metastatic processes in Hs578T and MDA-MB-468 breast cancer cells and in breast cancer in vivo via NF-kappa B signaling, a pathway which was also picked up in the current study." (PMID 36674861, 2023). "We also reported C1QBP expression in TNBC and other breast cancers, tested C1QBP correlation with clinicopathological factors and its role in promoting metastasis." (PMID 33708767, 2021). "When mice received Zfra4-10 or WWOX7-21 peptide alone followed by 4T1 breast cancer inoculation, these mice developed endogenous complex formation of WWOX with many target proteins, including ERK, C1qBP, NF-κB, Iba1, p21, CD133, JNK1, COX2, Oct4, and GFAP in the spleen, brain, and lung." (PMID 32764489, 2020). "High mRNA expression levels of C1QBP were significantly associated with poor disease‐free survival (DFS) specifically in patients with TNBC; however, its prognostic value was not significant across all breast cancer patients." (PMID 39748215, 2025).
pancreatic cancer (10 papers, 2019 to 2024). "C1QBP was proved to be enriched in the exosomes secreted by the pancreatic cancer cells, leading to the education of the liver to form a pro-metastatic microenvironment." (PMID 35711850, 2022). "Our previous study reported that insulin/IGF-1 stimulates Complement component 1, q subcomponent binding protein (C1QBP), to mediate anti-apoptosis and invasion of pancreatic cancer." (PMID 35252207, 2022). "There is a report that the silencing of C1QBP inhibited hepatic metastasis of pancreatic cancer cells in vivo." (PMID 34067437, 2021). "A recent research showed that Pancreatic ductal adenocarcinoma derived exosome carried CD44v6/ C1QBP complex to promote pancreatic cancer liver metastasis." (PMID 34527419, 2021).
viral infection (10 papers, 2013 to 2025). "Go enrichment analysis showed that DEGs were enriched by the response to the virus, activation of the innate immune response, negative regulation of the viral genome, and defense response to the virus, indicating that C1QBP is closely associated with virus infection." (PMID 40454173, 2025). "The membrane form of C1qbp is currently reported to play a role in viral infection, and it is recognized as an essential pathogen recognition receptor." (PMID 38773982, 2024). "Given that induction of RIG-1 inhibits EBOV replication we speculate that EBOV-MBL complexes activate C1QBP which then negatively regulates RIG-1 inhibition of viral infection, thereby enhancing viral proliferation." (PMID 23573288, 2013).
lung carcinoma (9 papers, 2016 to 2024). "To investigate the expression level of C1QBP in clinical specimens, we analyzed the microarray datasets of lung cancer and normal counterparts, using the Oncomine database." (PMID 30991713, 2019). "Expression of C1QBP was significantly upregulated in all available datasets for lung cancer in the Oncomine database." (PMID 30991713, 2019). "According to our previous transcriptomic analysis, PAH and lung cancer have three (C1QBP, COX6B1, and SLC12A8) common overregulated genes located in the transmembrane helix related to negative regulation of transcription by RNA polymerase II and chemical carcinogenesis-reactive oxygen species." (PMID 39791702, 2024). "Knockdown of C1QBP reduces lamellipodia formation and cancer metastasis in lung carcinoma cells." (PMID 30991713, 2019). "Previously, high expression of C1QBP was also reported in lung cancer cells and tissues." (PMID 30991713, 2019). "Next, we focused on lung cancer due to the high expression of C1QBP according to the GNET database." (PMID 30991713, 2019). "Further analysis confirmed that endogenous C1QBP could be immunoprecipitated with endogenous RASSF2 from H441 lung cancer cells, which contain an activated Ras, suggesting the interaction is physiologically relevant." (PMID 26999212, 2016). "It is found that 3 of the 10 SFs are reported to be connected with lung cancer, namely LSM7, C1QBP, and THOC1." (PMID 35126467, 2021).